TRAF4 (TNF receptor associated factor 4)
Diseases named in the same sentence as TRAF4 in open-access papers (continued):
Sharing a sentence is not in itself a finding about the gene and the disease.
inflammation (1 paper, 2023). Aberrant reaction of the microcirculation characterized by movement of fluid and leukocytes from the blood into extravascular tissues. "TRAF4-deficient mice showed attenuated OVA-induced or IL-25–induced (IL-17E) type 2 pulmonary inflammation, implying that TRAF4 is an important regulator in these processes." (PMID 37607012, 2023). "T cell–intrinsic TRAF4 is critical for the expansion of ST2+ mTh2 cells in IL-33–induced airway inflammation." (PMID 37607012, 2023). "OVA323-339 peptide induced similar low-grade eosinophilic airway inflammation, as indicated by the numbers of eosinophils (CD45+CD11b+SiglecF+) in the BAL, of both TRAF4-sufficient and TRAF4-deficient mice." (PMID 37607012, 2023).
neurodegenerative disease (1 paper, 2012). A disorder of the central nervous system characterized by gradual and progressive loss of neural tissue and neurologic function. "Altogether, these results provide conclusive evidence for the pivotal contribution of TRAF4 to myelination and to cerebellar homeostasis, and link the loss of TRAF4 function to demyelinating or neurodegenerative diseases." (PMID 22363515, 2012).
TRAF4 also shares sentences with these, for which no sentence is quoted: oesophageal cancer (3 papers); allergic disease (1); bone cancer (1); cerebellar ataxia (1); chronic lymphocytic leukemia (1); Down syndrome (1); food allergy (1); Graves disease (1); hepatoblastoma (1); invasive ductal carcinoma (1); malignant glioma (1); marginal zone lymphoma (1); melanoma (1); pancreatic adenocarcinoma (1); radiation injury (1); rectum adenocarcinoma (1); skin tumour (1); triple-negative breast carcinoma (1); uterine corpus endometrial carcinoma (1).